LYZ (lysozyme)
Diseases named in the same sentence as LYZ in open-access papers (continued):
Sharing a sentence is not in itself a finding about the gene and the disease.
Nephropathy (11 papers, 2019 to 2025). A nonspecific term referring to disease or damage of the kidneys. "The determination of the lysozyme concentration in physiological fluids can be used for the diagnosis of a number of diseases: pleural tuberculosis, intra-abdominal abscesses, lysozyme-associated nephropathy and various conjunctival diseases." (PMID 38397407, 2024). "Following the etiological investigation, lysozyme-induced nephropathy was believed to be the most probable cause of renal injury." (PMID 36865968, 2023). "Reduction in peripheral monocyte counts following treatment was associated with stabilization or improvement in renal function in several cases, supporting the hypothesized causal role of lysozyme in the pathogenesis of nephropathy." (PMID 41181405, 2025). "One patient had a detectable cryoglobulinemia associated with a diagnosis of lysozyme nephropathy." (PMID 38106568, 2023). "In this cohort of patients with CMML with a kidney injury, the 2 most frequent kidney complications were lysozyme-induced nephropathy, and kidney infiltration by the CMML." (PMID 38106568, 2023). "In this cohort of patients with CMML with a kidney injury, the 2 most frequent renal complications were lysozyme-induced nephropathy and renal infiltration by the CMML." (PMID 38106568, 2023). "Lysozyme-induced nephropathy is characterized by acute tubular injury with abundant cytoplasmic granular inclusions that stain strongly for lysozyme." (PMID 38106568, 2023). "Fourteen patients (87.5%) underwent a kidney biopsy, and the 2 main pathological findings were lysozyme nephropathy (56%) and renal infiltration by the CMML (37.5%)." (PMID 38106568, 2023). "This case highlights the importance of recognizing lysozyme-induced nephropathy as a form of kidney injury in AML." (PMID 36865968, 2023). "We found that lysozyme nephropathy and an infiltration by the CMML were by far the most frequent kidney diseases associated with CMML." (PMID 38106568, 2023). "The 2 most frequent diagnoses were lysozyme nephropathy (n = 9, 56%), and an interstitial infiltrate compatible with a CMML infiltration in the kidney (n = 6, 37.5%)." (PMID 38106568, 2023). "When the capacity for reabsorption is overwhelmed by sustained lysozyme overproduction, nephropathy may develop, signaling either a high disease burden or the presence of specific risk factors." (PMID 41181405, 2025). "Four patients with lysozyme nephropathy had also lysozymuria." (PMID 38106568, 2023). "The following rare case will describe a case of lysozyme nephropathy in a patient without any underlying hematological malignancy, but instead with systemic granulomatous disease." (PMID 38028084, 2023). "In addition, these 106 potential classifiers/biomarkers between TCMR vs. STA are associated with kidney damage (e.g., ATP1B1, CST3, FAH, GSS, HPX and LYZ), tubule injury (e.g., CRYM, GSS, HAGH, HPX and LYZ) and kidney inflammation (e.g., DCN)." (PMID 36814924, 2023). "Importantly, lysozyme-induced nephropathy can respond to renal supportive care and cytorectuction, arguing for a monitoring of lysozymuria in patients with CMML, and if necessary a renal biopsy to confirm the diagnosis." (PMID 38106568, 2023). "Among the three cases of unilateral PKD discovered in this study, P45’s case may have been caused by an HNF1B mutation, while P46 and P47 had no gene mutations on the kidney disease panel and P47 had LYZ, FGA, and GLI3 heterozygous mutations on the WES." (PMID 31056860, 2019).
periodontal disease (11 papers, 2007 to 2024). "Concentrations of certain salivary parameters related to periodontal disease in humans, namely α-amylase, lysozyme, lactate dehydrogenase, calcium, and phosphorus, have been quantified in a population of healthy dogs." (PMID 35565518, 2022). "There has been little information on the clinical application of the nutritional uptake of lysozyme or carbazochrome for periodontal disease." (PMID 30845920, 2019). "In this study, calcium, phosphorus, lysozyme, LDH, and amylase were measured in saliva of both healthy dogs (Group 1) and in dogs with different grades of periodontal disease (Groups 2 and 3)." (PMID 35565518, 2022). "The results showed that IgE, histamine, and lysozyme concentrations in patients with asthma and periodontal disease were considerably higher than those in individuals without periodontal disease or asthma." (PMID 37959214, 2023). "This study evaluated whether salivary alpha-amylase, lysozyme, lactate dehydrogenase (LDH), calcium, and phosphorus can be used as markers of periodontal disease in dogs." (PMID 35565518, 2022). "Although lysozyme activity has not been correlated with either gingival inflammation or age (this report), the interpretation that increased levels of PGE2 may be linked to periodontal disease and/or aging supports the notion that the oral cavity may be in a state of chronic low inflammation." (PMID 18159234, 2007).
Sepsis (11 papers, 2015 to 2025). Sepsis is defined as life-threatening organ dysfunction caused by a dysregulated host response to infection. "UMAP embedding of LYZ+ monocytes and nearest neighbor differential abundance analysis unveiled a significant loss of ncMonos in patients with late sepsis compared with healthy controls." (PMID 40251340, 2025). "No matter in the CRRT group or the non-CRRT group, Serum LYZ levels were increased on the 7th day compared with the1st day, which suggests that elevated serum LYZ levels may be associated with sepsis recovery." (PMID 36650427, 2023). "The proportion of CSF3R neutrophils and LYZ neutrophils was decreased in the sepsis group compared to healthy control group." (PMID 40149573, 2025). "To determine the function of Vangl2 during LPS-induced sepsis, we specifically ablated Vangl2 in myeloid cells by crossing Vangl2flox/flox mice with mice expressing lysozyme proximal promoter (Lyz2-Cre)." (PMID 39269442, 2024). "Based on the serum proteomic analysis in patients with sepsis before and after CRRT, elevated serum LYZ and LRG1 levels are associated with clinical benefits of CRRT during sepsis recovery." (PMID 36650427, 2023). "This pilot study indicated that serum LYZ and LRG1 levels were significantly associated with sepsis recovery contributed by CRRT in pediatric patients." (PMID 36650427, 2023). "Considering the novelty of LYZ as an indicator of sepsis recovery and clinical benefits of CRRT, the underlying mechanisms of LYZ involved in roles of CRRT in pediatric sepsis is worth of more attention in the future." (PMID 36650427, 2023). "In the sepsis group, the expression levels of LYZ and HD-5 (both P < 0.001) were significantly reduced as compared to the control counterparts." (PMID 36088483, 2022). "We found that increased the expression levels of TLR4 in the ileal tissues of sepsis mice exacerbated intestinal damage, increased mortality rates, promoted the depletion of Paneth cell and reduced the expression of LYZ and DEF-5." (PMID 36088483, 2022). "Elevated serum LYZ and LRG1 levels are associated with clinical benefits of CRRT during sepsis." (PMID 36650427, 2023). "This suggests that LYZ may affect the pathogenesis of sepsis by affecting coagulation, liver function, or fluid leakage." (PMID 36650427, 2023). "However, among mice treated with TAK-242, the expression levels of LYZ (P = 0.0009) and HD-5 (P < 0.0001) had more than two-fold increased as compared to mice in the sepsis group." (PMID 36088483, 2022). "Though confirmed in a larger-scale population, LYZ and LRG1 was screened as novel biomarkers of sepsis recovery contributed by CRRT as an adjuvant therapy." (PMID 36650427, 2023). "Secondly, among screened 6 proteins, only LYZ and LRG1 were validated to be potential biomarker for assessing the progression of sepsis and clinical benefits of CRRT in pediatric patients with sepsis." (PMID 36650427, 2023). "LYZ and LRG1 might be valuable indicators for assessing the clinical benefits of CRRT in pediatric patients with severe sepsis." (PMID 36650427, 2023). "Leukocytic immunoreactivity of lactoferrin (LF) and lysozyme (LZ) was investigated on lung samples obtained from autopsy cases of sepsis-related (n = 13) and non-sepsis-related fatalities (n = 14)." (PMID 33092081, 2020). "Since no significant immunoreactivity differences were detected between sepsis and non-sepsis cases, lysozyme (LZ) is the only marker tested, which was not considered suitable for a post-mortem diagnosis of sepsis." (PMID 33092081, 2020).
tuberculosis (11 papers, 2015 to 2025). A chronic, recurrent infection caused by the bacterium Mycobacterium tuberculosis. "Several endogenous AMPs, such as lactoferrin, human β−Defensin, LL-37, granulysin and lysozyme have been associated with protection against tuberculosis." (PMID 38900248, 2024). "In our multivariate analysis, normal lysozyme was significantly associated with tuberculosis." (PMID 38787250, 2024). "In tuberculosis, lysozyme was measured in 30.2% of tuberculosis patients (n = 19) and elevated in 12.7% of the total tuberculosis group (n = 8) (p < 0.001)." (PMID 38787250, 2024). "The possible role of lysozyme in protection against tuberculosis was first indicated more than 40 years ago using egg white lysozyme." (PMID 38900248, 2024). "It has been reported that PMT deficiency increased CW permeability of Mycobacterium abscessus leading to the reduction in anti-tuberculosis drugs and lysozyme tolerance." (PMID 34276591, 2021). "The salivary glands are usually spared of tuberculosis because of thiocyanate ions and proteolytic enzymes such as lysozyme that confer antibacterial action." (PMID 26175833, 2015). "Based on these findings we hypothesize, that lysozyme contributes to protection against early-stage tuberculosis." (PMID 38900248, 2024). "High lysozyme levels can be found in infectious uveitis (tuberculosis, syphilis)." (PMID 33466638, 2021). "Based on this pioneering study lysozyme was detected in high levels in BCG-vaccinated rabbits, alveolar macrophages, granulomas of mycobacteria-infected rabbits and in serum and bronchoalveolar lavage of tuberculosis patients." (PMID 38900248, 2024). "Blood workup (including CBC, hemoglobin electrophoresis (for sickle cell disease), RPR, FTA-ABS, Quantiferon Gold for tuberculosis, angiotensin converting enzyme, and lysozyme) and chest radiograph were all negative." (PMID 38132210, 2023).
dental caries (10 papers, 2015 to 2025). The decay of a tooth, in which it becomes softened, discolored, and/or porous. "Also, ECC may have a relationship with lower concentrations of unstimulated salivary lactoferrin and lysozyme, which may act as a risk factor for dental caries in children." (PMID 26236438, 2015). "A chewing gum containing DexA70 and lysozyme followed by mouthwash containing antimicrobial chemical reagents of lower concentration have great potential to be a better solution for dental caries with minimized side effects." (PMID 34650538, 2021). "DexA70 treatment markedly enhances biofilm sensitivity to antimicrobial agents and lysozyme, indicating its great potential in combating biofilm-related dental caries." (PMID 34650538, 2021). "The studies included in this review do not allow us to conclude whether there is, in fact, any association between salivary levels and/or activities of lysozyme, lactoferrin, and PR3 with oral health or with dental caries." (PMID 37780687, 2023). "Flow rate, buffer capacity, inorganic components, and antimicrobial factors such as lysozyme and lactoferrin are among the special characteristics of saliva, which may have important roles in dental caries prevention." (PMID 26236438, 2015). "Hao et al25 stated that lysozyme amount difference between two groups of caries free children and children who had dental caries (dmft>5) was not statistically significant." (PMID 26236438, 2015). "The treatment of dental caries and its correlation with the change in salivary lactoferrin and lysozyme levels has not been well-established." (PMID 26236438, 2015).
hereditary amyloidosis (10 papers, 2012 to 2025). Hereditary amyloidosis refers to a group of inherited conditions that make up one of the subtypes of amyloidosis. "Hereditary amyloidosis cases, such as those associated with mutations in gelsolin, cystatin C, or lysozyme, typically occur in younger individuals or as part of familial syndromes." (PMID 40700073, 2025). "Hereditary amyloidosis with a variant lysozyme of p.Trp82Arg presented with dominant kidney involvement was firstly reported in a Chinese family." (PMID 31395023, 2019). "Similarly, the aggregation of human lysozyme, which occurs in a certain case of hereditary amyloidosis linked to specific lysozyme mutations, were observed both in vitro and in cells using dSTORM and showed similar morphological features." (PMID 28809165, 2016). "Hereditary amyloidosis refers to a wide spectrum of rare diseases with different causative mutations in the genes of various proteins including transthyretin, apolipoprotein AI and AII, gelsolin, lysozyme, cystatin C, fibrinogen Aα-chain, β2-microglobulin, apolipoprotein CII and CIII." (PMID 30665372, 2019). "Molecular and genetic testing can be performed in cases of hereditary amyloidosis (e.g., TTR, fibrinogen, lysozyme, apolipoproteins AI and AII, and gelsolin)." (PMID 39597824, 2024).
influenza (10 papers, 2013 to 2024). An acute viral infection of the respiratory tract, occurring in isolated cases, in epidemics, or in pandemics; it is caused by serologically different strains of viruses (influenzaviruses) designated A, B, and C, has a 3-day incubation period, and usually lasts for 3 to 10 days. "The following is an overview of studies on the activity of lysozyme against different types of viruses involved in influenza and related respiratory diseases." (PMID 38338396, 2024). "To this end, we immunized mice intranasally with a quadrivalent influenza HA vaccine containing A/California/7/2009 HA together with cultured oral bacteria or lysozyme." (PMID 34399617, 2021). "In this study, we investigated the potential of lysozyme-treated Enterococcus faecalis FK-23 (LFK) to prevent influenza in influenza virus-infected mice." (PMID 23853748, 2013). "We previously reported that oral administration of the soluble components of LFK, lysozyme-treated lactic acid bacteria E. faecalis FK-23, has an anti-influenza effect by upregulation of the anti-inflammatory cytokine IL-10 in lung." (PMID 23853748, 2013). "Animals expressing the control anti-lysozyme specific nanobody cAb1-mIgG2a and those given PBS showed symptoms of influenza including difficulty in breathing, pinched waists and sunken abdomen 3 days post-challenge." (PMID 32547534, 2020). "Lactoferrin may inhibit influenza virus, although we are not aware of anti‐influenza actions of lysozyme." (PMID 34676696, 2021).
leukemia (10 papers, 2014 to 2025). A malignant (clonal) hematologic disorder, involving hematopoietic stem cells and characterized by the presence of primitive or atypical myeloid or lymphoid cells in the bone marrow and the blood. "Urinary lysozymuria associated with monocitic and myelomonocitic leukemia was found in a classic work to range between 25 and 420 μg/mL of lysozyme." (PMID 33804443, 2021). "SPR chips were modified using lysozyme imprinted polymeric nanoparticles to detect the changes in lysozyme levels, which work as indicators for some diseases including leukemia, meningitis, several kidney problems, and rheumatoid arthritis." (PMID 32549390, 2020). "High levels of lysozyme may indicateinfection in the wound fluid, bacterial meningitis in the cerebrospinalfluid, and leukemia in urine." (PMID 40657126, 2025). "However, in leukemias with circulating myelocytes, this mechanism can be overwhelmed and lead to high levels of non‐albumin proteinuria from the lysozyme itself." (PMID 36051078, 2022). "Furthermore, the salivary defense system which contains various antimicrobial components such as secreted immunoglobulin A (SIgA), α-amylase and lysozyme, has been reported to be significantly impaired in leukemia." (PMID 25025462, 2014). "Elevated levels of LYZ in serum and urine were previously observed in cases of monocytic and monomyelocytic leukemia, suggesting that LYZ could potentially serve as a biomarker for these leukemias and related kidney injury." (PMID 40046560, 2025).
melanoma (10 papers, 1976 to 2025). A malignant, usually aggressive tumor composed of atypical, neoplastic melanocytes. "This pattern suggests that LYZ may play a protective role during the early stages of melanocytic transformation and tumor progression, but its downregulation is associated with melanoma metastasis." (PMID 41148223, 2025). "In contrast, LYZ displayed elevated expression in nevus and primary melanoma but decreased levels in MM, aligning with its protective role identified through MR, SMR analysis, and Cox regression." (PMID 41148223, 2025). "In contrast to other proteins such as CCL11 and LYZ, whose roles in melanoma are relatively well-established, CD72 represents a less-characterized but promising target." (PMID 41148223, 2025). "Among these, CD72 and LYZ emerged as promising therapeutic targets, supported by prognostic and predictive value in multiple melanoma cohorts." (PMID 41148223, 2025). "Through additional comparison between normal skin, benign nevus, primary melanoma, and MM, we found that previously protective putative gene LYZ expression in normal skin is relatively low, while both nevus and primary melanoma samples display elevated levels, which then markedly decrease in MM." (PMID 41148223, 2025). "The rise in serum lysozyme activity was not due to renal damage or any infective process and in the case of malignant melanoma was shown to be associated with infiltration of the tumour mass by macrophages." (PMID 938609, 1976). "We defined clusters corresponding to melanoma (PMEL, MLANA), immune infiltrates (TRBC2, TRAC, TMSB4X), melanophages (CD74, LYZ), keratinocytes (KRT14, TRIM29), blood vessels (CAVIN1, PECAM), and fibroblast‐enriched areas in the dermis (DCN, COL1A2, FBLN1)." (PMID 39846232, 2025).
E. coli infection (9 papers, 2014 to 2024). "In piglets, the addition of lysozyme to dietary supplements can improve the development and function of the intestine and protect against enterotoxigenic Escherichia coli infection." (PMID 38791637, 2024). "There was no significant change in the concentration of LYZ in GED goats prior to E. coli infection; however, there was a significant increase in LYZ concentration following infection." (PMID 39099401, 2024). "The host’s immunological system, however, demonstrates an ability to protect itself from E. coli infection thanks to components of innate immunity components, such as anti-microbial peptides, lysozyme, lactoferrin and other complements." (PMID 38734661, 2024). "In pigs, lysozyme supplementation alleviates intestinal injury and inflammation in a malnutrition and enterotoxigenic Escherichia coli infection model." (PMID 37582766, 2023). "Since lysozyme can effectively decreased the number of E. coli and inhibit E. coli infection, the rhLZ transgenic pigs have an important breeding value." (PMID 24586544, 2014). "Results with lysozyme at 1 DAF showed that LysA was significantly upregulated in the anterior midgut after S. aureus infection (p < 0.01) while LysB was significantly downregulated after E. coli infection (p < 0.01)." (PMID 24885969, 2014). "During E. coli infection, GED goats exhibited increased LYZ in the mammary glands, improving their disease resistance." (PMID 39099401, 2024). "Given that lysozyme and endolysin have antimicrobial activity, these attributes suggest that the proteins can be used as an antibacterial agent to combat AMR E. coli infections." (PMID 38052835, 2023).